EDEM1 (ER degradation enhancing alpha-mannosidase like protein 1)
Description:
Extracts misfolded glycoproteins, but not glycoproteins undergoing productive folding, from the calnexin cycle. It is directly involved in endoplasmic reticulum-associated degradation (ERAD) and targets misfolded glycoproteins for degradation in an N-glycan-independent manner, probably by forming a complex with SEL1L. It has low mannosidase activity, catalyzing mannose trimming from Man8GlcNAc2 to Man7GlcNAc2.
Synonyms: EDEM; KIAA0212
Tractability: Antibody: UniProt predicts a signal peptide or a membrane-spanning region. PROTAC: ubiquitination databases record sites on it.
Gene: Protein-coding gene on chromosome 3 (5,187,646 to 5,219,958, forward strand). Ensembl gene ENSG00000134109.
Subcellular location: Endoplasmic reticulum membrane
Subcellular location (Human Protein Atlas): Endoplasmic reticulum; Aggresome
Pathways (Reactome):
Cellular responses to stimuli: XBP1(S) activates chaperone genes
Metabolism of proteins: ER Quality Control Compartment (ERQC)
Gene Ontology:
Molecular function: mannosyl-oligosaccharide 1,2-alpha-mannosidase activity; misfolded protein binding; protein binding; calcium ion binding
Biological process: endoplasmic reticulum mannose trimming; ERAD pathway; positive regulation of retrograde protein transport, ER to cytosol; protein targeting to ER; ubiquitin-dependent protein catabolic process; mannose trimming involved in glycoprotein ERAD pathway; carbohydrate metabolic process
Cellular component: endoplasmic reticulum; endoplasmic reticulum quality control compartment; endoplasmic reticulum membrane; membrane
Genetic constraint (gnomAD): Loss-of-function variants: 60 observed, 66.74 expected, observed/expected ratio (o/e) 0.9, 90% interval 0.73 to 1.12. The synonymous counts are far from expectation, so gnomAD's model fits this gene poorly and the ratio says little. Missense variants: 879 observed, 773.65 expected, observed/expected ratio (o/e) 1.14, 90% interval 1.07 to 1.2. Synonymous variants: 368 observed, 304.18 expected, observed/expected ratio (o/e) 1.21, 90% interval 1.11 to 1.32.
Homologues: Orthologues: chimpanzee EDEM1 (99% identical), macaque EDEM1 (98% identical), pig EDEM1 (96% identical), dog EDEM1 (94% identical), guinea pig EDEM1 (93% identical), mouse Edem1 (92% identical), rat Edem1 (92% identical), tropical clawed frog edem1 (70% identical), zebrafish edem1 (69% identical), rabbit EDEM1 (54% identical), Caenorhabditis elegans C47E12.3 (47% identical). Paralogues in human: EDEM3 (35% identical), EDEM2 (35% identical), MAN1B1 (26% identical), MAN1C1 (23% identical), MAN1A2 (23% identical), MAN1A1 (22% identical).
Diseases named in the same sentence as EDEM1 in open-access papers:
EDEM1 is named in the same sentence as 35 diseases in open-access papers, as found by Europe PMC text mining. Sharing a sentence is not in itself a finding about the gene and the disease. The quoted sentences say what the papers report.
melanoma (6 papers, 2012 to 2025). A malignant, usually aggressive tumor composed of atypical, neoplastic melanocytes. "Conversely, miR-211, a known transcriptional target of MITF, is induced in melanotic melanoma cells, where it targets EDEM1 and consequently impairs the degradation of TYROSINASE (TYR) through the ER-associated degradation (ERAD) pathway." (PMID 28445987, 2017). "All together, these results indicate that, in melanotic melanoma cells, miR-211 is induced by BRAFi/MEKi and favors their pro-pigmentation activity by targeting EDEM1, hence promoting TYR expression and melanin accumulation." (PMID 28445987, 2017). "Here, we investigate the role of EDEM1 in the processing of tyrosinase, a tumour antigen overexpressed in melanoma cells." (PMID 22905195, 2012). "Accelerating tyrosinase degradation by EDEM1 overexpression may lead to an efficient antigen presentation and enhanced elimination of melanoma cells." (PMID 22905195, 2012). "Whether EDEM1 may play an active role in the enhanced antigen presentation of tyrosinase peptides in melanoma cells is currently under investigation." (PMID 22905195, 2012). "In melanotic melanoma cells, miR‐211 acts as a direct target of MITF and regulates EDEM1 expression and cell migration, subsequently impairing the degradation of Tyrosinase." (PMID 39823244, 2025). "Consistent with our in vitro findings, genes associated with the ATF4 (e.g., ATF4, DDIT3, PPP1R15A and CHAC1), ATF6 (e.g., ATF6B, CALR, SEL1L, and EDEM1) and XBP1 (e.g., SSR3 and DELR1) pathways were significantly enriched in melanoma TILs compared with healthy blood T cells." (PMID 40335738, 2025). "Moreover, the mRNA expressions of two critical XBP1 target genes ERDJ4 and EDEM1 were also significantly correlated with PTPRC, CD8A and IFNG, respectively, indicating the potential facilitative role of IRE1α-dependent UPR branch in anti-tumor immunity in melanoma." (PMID 38291473, 2024). "Overexpression of EDEM1 in melanoma cells could be an efficient way of accelerating tyrosinase degradation and inducing a more efficient display of peptides at the surface of the melanoma cell leading to an efficient recognition by CTL and the eventual enhanced elimination of melanoma cells." (PMID 22905195, 2012).
breast carcinoma (2 papers, 2025 to 2026). "We found that >3 LN metastases and EDEM1 expression were independent prognostic risk factors for the OS of breast cancer." (PMID 40735463, 2025). "The results indicated that high expression of EDEM1 was prominently associated with ER status and PR status in breast cancer (P < 0.001), indicating a potential role of EDEM1 in breast cancer progression, especially TNBC progression." (PMID 40735463, 2025). "Through analyzing the IHC scores of 131 patients with breast cancer, we found that the high EDEM1 expression was associated with poor prognosis of breast cancer patients." (PMID 40735463, 2025). "Furthermore, the expressions of EDEM1 were associated with worse clinical outcomes in breast cancer patients." (PMID 40735463, 2025). "Moreover, high EDEM1 expression was associated with poor prognosis in breast cancer patients." (PMID 40735463, 2025). "Similar results were also obtained in tissues from our cohort: EDEM1 was increased in the majority of the breast cancer tissues." (PMID 40735463, 2025). "To reveal the clinical prognostic prediction value of EDEM1 in breast cancer, we collected tumor tissues from 131 breast cancer patients." (PMID 40735463, 2025). "Uniformly, the immunohistochemistry (IHC) analysis was performed on tumor tissues and adjacent normal tissues, and proved that EDEM1 was up-regulated in breast cancer tissues in most patients (23/25)." (PMID 40735463, 2025). "Firstly, Kaplan–Meier analysis showed that breast cancer patients with high EDEM1 expression had poor overall survival (OS) and disease-free survival (DFS)." (PMID 40735463, 2025). "We gathered the clinical features and prognosis information of these 131 breast cancer patients and performed IHC staining to evaluate EDEM1 expression in these breast cancer tissues." (PMID 40735463, 2025). "Taken together, our findings identified EDEM1 as a potential therapeutic target and prognostic indicator for breast cancer, especially TNBC treatment in the future." (PMID 40735463, 2025). "We further detected the differential expression of EDEM1 between human breast cancer tissues and normal tissues in The Cancer Genome Atlas and Metabric databases, and up-regulated mRNA expression of EDEM1 was found in breast cancer tissues." (PMID 40735463, 2025). "It was also found that the expression of EDEM1 was markedly up-regulated in both breast cancer cells and tissues." (PMID 40735463, 2025). "Clinically, high EDEM1 expression is correlated with poor patient outcomes in breast cancer, especially in TNBC patients treated with DOX-based chemotherapy." (PMID 40735463, 2025). "Meanwhile, >3 LN metastases, distant metastasis, and EDEM1 expression were proved to be independent prognostic indicators for DFS of breast cancer." (PMID 40735463, 2025). "We further explored the biological functions of miR-32-5p in breast cancer and conducted rescue experiments to elucidate its regulatory effect on EDEM1." (PMID 40735463, 2025). "Besides, EDEM1 expression was also elevated in breast cancer tissues treated with DOX during neoadjuvant chemotherapy, further strengthening the relationship between EDEM1 expression and DOX resistance." (PMID 40735463, 2025). "Considering the up-regulated EDEM1 expression in breast cancer, we wonder whether EDEM1 served as a tumor promoter in TNBC." (PMID 40735463, 2025). "To investigate the potential roles of EDEM1 in breast cancer, we examined its differential expression between normal cells and breast cancer cells and found that EDEM1 is highly expressed in most breast cancer cells compared with human normal mammary epithelial cells (MCF-10A)." (PMID 40735463, 2025). "Our study not only demonstrated the crucial role of EDEM1 in DOX-induced ER stress but also provided a potential therapeutic target and prognostic predictor for breast cancer patients." (PMID 40735463, 2025).
breast carcinoma (continued). "Then, a chi-square test was used to evaluate the correlations between EDEM1 expression and clinicopathologic features of breast cancer patients, and no noticeable difference was found between the 2 groups." (PMID 40735463, 2025). "Considering that the clinical relevance and prognostic value of EDEM1 in breast cancer have not been fully investigated, we further explored the prognostic value of EDEM1." (PMID 40735463, 2025). "Since the function of EDEM1 in breast cancer progression and chemoresistance has not been fully studied, we first carried out functional experiments in vitro and found that EDEM1 can promote the proliferation, metastasis, and DOX resistance of TNBC cells." (PMID 40735463, 2025). "Furthermore, though DOX suppressed the growth of breast cancer cells, these suppressive effects were more substantial in the control group rather than the EDEM1 overexpression group, which indicated that EDEM1 could attenuate the anticancer effect of DOX." (PMID 40735463, 2025). "Similar to ER + breast cancer cells, ER-negative and non-tumorigenic breast cell lines, which lack BRRIAR expression but retain H3K27ac binding at the 5’ and 3’ ends of the enhancer cluster, showed strong interactions between the enhancer and BHLHE40, and a weaker interaction with EDEM1." (PMID 41501810, 2026).
colorectal cancer (2 papers, 2021 to 2025). A primary or metastatic malignant neoplasm that affects the colon or rectum. "For example, EDEM1 was related to cancer progression and poor prognosis in lung adenocarcinoma and colorectal cancer." (PMID 40735463, 2025). "Meanwhile, several studies proved EDEM1 as a prognostic indicator in female lung adenocarcinoma and colorectal cancer." (PMID 40735463, 2025).
osteosarcoma (2 papers, 2019 to 2021). A usually aggressive malignant bone-forming mesenchymal neoplasm, predominantly affecting adolescents and young adults. "ERAD is regulated by several tuner proteins, such as ER degradation-enhancing alpha-mannosidase-like 1 (EDEM1) and Osteosarcoma amplified 9 (OS-9)." (PMID 31083507, 2019).
viral infection (2 papers, 2018 to 2023). "Many studies demonstrated that EDEM-1 increases during virus infection or directly interacts with the viral proteins." (PMID 30241539, 2018). "The results showed that EDEM1 gene, calreticulin, and calnexin mRNA levels were all not modified in cp BVDV-infected MDBK cells, indicating that viral infection did not activate the ATF6 and XBP1 signaling pathways." (PMID 36939351, 2023).
ZIKV infection (2 papers, 2018 to 2025). "Consistent with this idea, induction of ER stress and the IRE1/XBP1 axis by treatment with tunicamycin (Tn) revealed both a potent splicing of the XBP1 mRNA and the induction of Erdj4 and Edem1 transcripts; thus, confirming a partial activation of XBP1s during ZIKV infection." (PMID 41157563, 2025). "However, ZIKV infection did not trigger the EDEM-1 to increase the degradation of misfolded and unfolded proteins which alleviated the accumulation of abnormal proteins." (PMID 30241539, 2018). "Therefore, the results implied that ZIKV infection mediates XBP1s to activate CHOP and may mediate cell apoptosis, but not EDEM-1 to activate protein degradation." (PMID 30241539, 2018).
asthma (1 paper, 2017). "In the lung, ORMDL3 activates the UPR via the ATF6 pathway, increasing transcription of endoplasmic reticulum–associated protein degradation pathway-specific genes (Edem-1) and regulating the expression of IL-6, which has been implicated in the pathogenesis of asthma." (PMID 27623174, 2017).
colitis (1 paper, 2017). Inflammation of the colon. "Consistently, GP supplementation reduced the protein expression of ATF-6 and mRNA expression of its downstream target genes Grp78, CHOP, Edem1, and Xbp1 in the HFD-fed DSS-colitis mice, showing the suppression of ER stress." (PMID 28524086, 2017).
Dengue (1 paper, 2007). "Furthermore, it was also reported that the XBP1 downstream genes such as EDEM1 and p58 (IPK) were induced in Dengue infected cells." (PMID 17888185, 2007).
diabetes (1 paper, 2023). "We propose EDEM1 as a regulator of the UPR via IRE1/XBP1s and IRE1/JNK/c-Jun signaling cascades and insulin transcription in pancreatic β-cells, supporting EDEM1 as a potential target for the treatment of diabetes." (PMID 37822496, 2023).
hepatocellular carcinoma (1 paper, 2023). A malignant tumor that arises from hepatocytes. "In conclusion, the inhibitory effect of FAM134B on hepatocellular carcinoma (HCC) cell autophagy is attributed to its suppression of endoplasmic reticulum stress‐related degradation factors, including DERL2, EDEM1, SEL1L and HRD1." (PMID 37728036, 2023).
Huntington disease (1 paper, 2024). Huntington disease (HD) is a rare neurodegenerative disorder of the central nervous system characterized by unwanted choreatic movements, behavioral and psychiatric disturbances and dementia. "EDEM1's enrichment profile varied between the high and low expression groups, with a predominant association with Huntington's disease and apoptosis, respectively (Fig. S9A1, A2)." (PMID 38965390, 2024).
liver cancer (1 paper, 2023). An epithelial or non-epithelial malignant neoplasm that arises from the liver. "FAM134B inhibits HCC cell autophagy and promotes the progression of liver cancer by inhibiting the expression of ER stress‐related degradation factors such as DERL2, EDEM1, SEL1L and HRD1." (PMID 37728036, 2023). "The results exhibited varying degrees of upregulation in the expression of DERL2, EDEM1, SEL1L and HRD1 in Hep3B cells of the sh‐FAM134B group when compared to the sh‐NC group (p < 0.05), indicating the effective induction of ER stress in Hep3B liver cancer cells by sh‐FAM134B." (PMID 37728036, 2023).
neuroblastoma (1 paper, 2021). Neuroblastoma (NB) is the most common solid, extracranial childhood tumor. "Here, using biochemical methods applied to human embryonic kidney, HEK293, and SH-SY5Y neuroblastoma cells, we show that EDEM1 is an important regulatory factor involved in APP metabolism." (PMID 35008544, 2021). "To verify the generality of APP regulation by the EDEM1 chaperone protein, we downregulated EDEM1 in SH-SY5Y neuroblastoma cells." (PMID 35008544, 2021).
prostate adenocarcinoma (1 paper, 2022). "We treated LNCaP (prostate adenocarcinoma cells) and RWPE-1 cells (normal prostatic epithelial cells) with 10 nM synthetic androgens (R1881) for 24 h and assessed gene expression of EDEM1, EDEM2 and EDEM3." (PMID 35897761, 2022). "We first looked in The Cancer Genome Atlas (TCGA) prostate adenocarcinoma (PRAD) Firehose cohort to compare EDEM1, EDEM2 and EDEM3 gene expression data in prostate adenocarcinoma tissue (n = 497) and normal prostate tissue (n = 52)." (PMID 35897761, 2022).
prostate carcinoma (1 paper, 2022). A carcinoma that arises from epithelial cells of the prostate gland. "To investigate the clinical implications of EDEM gene upregulation, we looked at EDEM1/2/3 mRNA expression in relation to disease-free survival in 471 prostate cancer patients in the TGCA PRAD cohort." (PMID 35897761, 2022). "In contrast, neither EDEM1 nor EDEM2 gene expression correlated with disease-free survival in prostate cancer patients." (PMID 35897761, 2022). "EDEM1 and EDEM2 were slightly increased in prostate cancer patients in two out of five cohorts, suggesting that they may play some role in ERAD in prostate cancer; however, their expression was in no way associated with disease-free progression." (PMID 35897761, 2022).
renal carcinoma (1 paper, 2025). A carcinoma arising from the epithelium of the renal parenchyma or the renal pelvis. "Proteasome inhibitors can suppress the growth of renal cancer cells by modulating the gene expression of EDEM1, a downstream effector molecule in the unfolded protein response (UPR), through inhibition of GPR78 expression." (PMID 41040512, 2025).
steatosis (1 paper, 2014). Increased lipid within the cytoplasm of cells. "We observed a significant overexpression of DNAJC3, EDEM1 (q value <0.01) and BIP (q value = 0.055) in patients with severe steatosis, and of DNAJC3 (q value = 0.023) and EDEM1 (q value = 0.014) in obese patients, compared with patients with no documented steatosis." (PMID 24973751, 2014).
thymoma (1 paper, 2021). A neoplasm arising from the epithelial cells of the thymus. "Stimulation of the thymoma cell line EL4 with Notch ligand Delta-like 4 (DLL4) induced expression of the genes involved in ERAD including Sel1l, Hrd1, Os9, and Edem1 as well as SEL1L proteins." (PMID 34240701, 2021).